PKNOX2-AS1 (PKNOX2 antisense RNA 1)
Synonyms: AP001007.1
Gene: Long non-coding RNA gene on chromosome 11 (125,258,626 to 125,266,798, reverse strand). Ensembl gene ENSG00000254932.
Diseases named in the same sentence as PKNOX2-AS1 in open-access papers:
PKNOX2-AS1 is named in the same sentence as 1 disease in open-access papers, as found by Europe PMC text mining. Sharing a sentence is not in itself a finding about the gene and the disease.
PKNOX2-AS1 shares sentences with these, for which no sentence is quoted: glioma (1 paper).